NOTCH2 (notch receptor 2)
Diseases named in the same sentence as NOTCH2 in open-access papers (continued):
Sharing a sentence is not in itself a finding about the gene and the disease.
melanoma (continued). "In our study, HH044 downregulated WNT5A, a contributor to Hedgehog signaling and a known druggable target for melanoma, and nNOS inhibition did not have a direct effect on Notch1 or Notch2 expression alone." (PMID 40574005, 2025). "Our data show that the absence of Notch1 or Notch2 tends to accelerate melanoma tumor development and growth." (PMID 36672468, 2023). "It is possible that BP mouse melanocytes that form melanoma do not express Notch1, and that the Notch1 expression seen in tumors from the Notch2 knockout group is a result of Notch2 knockout, i.e., compensating for the loss of Notch2 expression." (PMID 36672468, 2023). "In addition, selected members of NFKB and NOTCH signaling pathways (IKBKB, NOTCH2, HES1, PRKCA) were strongly overrepresented in CD271+ melanoma-initiating cells." (PMID 31118427, 2019).
hepatocellular carcinoma (22 papers, 2015 to 2026). A malignant tumor that arises from hepatocytes. "Stably downregulating NOTCH2 in hepatocellular carcinoma cell lines leads to attenuated cell invasion and migration potential and tumorigenicity in vivo, accompanied by histological maturation." (PMID 37728427, 2023). "The collaboration between GAS41 and lncAKHE activates the NOTCH2 pathway, which plays a critical role in controlling the apoptosis of hepatocellular carcinoma cells." (PMID 37853482, 2023). "NOTCH2 activation causes HES1 overexpression, proliferation, immature morphology and invasion in an acute kidney injury model and hepatocellular carcinoma model." (PMID 37728427, 2023). "NOTCH2 modulates compensatory hepatocyte proliferation in the damaged liver of mice and is positively related to more favorable clinical outcomes of hepatocellular carcinoma." (PMID 35322757, 2022). "Mechanistically, lncAKHE cooperated with YEATS4 to enhance the activation of NOTCH2 signaling which is usually abnormally upregulated in hepatocellular carcinoma." (PMID 29706630, 2018). "In human hepatocellular carcinoma, Notch2 regulates the stemness of liver CSCs via upregulation of NRARP, HES1 and HES6." (PMID 30285832, 2018). "In addition to NOTCH2, mutations in ARID2, a possible tumor suppressor, are also found in hepatocellular carcinomas." (PMID 31480474, 2019). "In hepatocellular carcinoma, DLL4/Notch1 generally drives tumor growth, whereas Jag1/Notch2 tends to suppress tumor progression." (PMID 41588437, 2026). "Loss of Notch2 in CD8+ T cells (but not of Notch1), has been shown to promote tumor growth in mice; and blockade of nuclear translocation of Notch2 intracellular domain (NIC), the active form of Notch, inhibits the cytotoxic efficacy of CD8+ T cells on hepatocellular carcinoma." (PMID 39491031, 2024).
lymphoma (21 papers, 2011 to 2025). A malignant (clonal) proliferation of B- lymphocytes or T- lymphocytes which involves the lymph nodes, bone marrow and/or extranodal sites. "As previously reported for mantle cell lymphoma, NOTCH1 and NOTCH2 mutations occurred mutually exclusively suggesting a similar oncogenic advantage for affected lymphoma cells." (PMID 36604606, 2023). "Arbo represents a NOTCH2 mutated model that is useful in MCL as well as other lymphomas with such mutation." (PMID 36467812, 2022). "NOTCH2 mutations have diagnostic and prognostic value for certain lymphomas that are predictive of adverse outcomes." (PMID 34299796, 2021). "Furthermore, molecular investigations performed at a clinical level have demonstrated a clear correlation between the risk of developing MALT, the main type of SGs lymphoma found in SjD patients, and mutations in the Notch2 gene." (PMID 41517433, 2025). "A potential transformation of MZL into DLBCL as part of the newly characterized C1 cluster of DLBCL may underlie the lymphoma in patient 05, as it carried a mutation of NOTCH2 that belongs to the frequently affected genes in splenic and nodal MZL." (PMID 33876323, 2021). "In addition, the authors compared mutated to wild type Notch 2 lymphomas regarding the clinical outcomes, reporting a shorter relapse-free survival, for cases carrying Notch 2 mutations." (PMID 33374160, 2020). "The truncate Notch2 receptor promotes lymphoma cell proliferation which may be associated with the activation of both the Notch2 and the NF-κB signaling, and there may be a cross-talk between the Notch2 and the NF-κB signals." (PMID 25314575, 2014). "Soluble factors derived from endothelial cells, such as Notch ligand Jagged1 (Jag1), induce Notch2-Hey1 signaling in lymphoma cells (LCs), contributing to chemoresistance in lymphoma." (PMID 38069225, 2023). "Subtype C1 shared alterations in certain pathways (e.g., NOTCH2) with low grade marginal zones lymphomas, and alterations in other NOTCH2 and BCL6 pathways were defining characteristics of this group." (PMID 36818048, 2023). "For instance, Notch2 is a key membrane receptor for B-cell function and plays a critical role in the pathogenesis of lymphoma." (PMID 36713586, 2022). "Due to their differential role in B and T-cell physiology, the Notch 2 member seems to be the most involved in lymphomagenesis even if a few Notch 1 signaling alterations were described in low as well as high grade lymphomas." (PMID 33374160, 2020). "In B cell lymphoma, Jag1 induced the expression of FGF4 which in turn activated Notch2 in lymphoma cells." (PMID 32028262, 2020). "NOTCH2, regulated by DTX1 protein, has been found recurrently mutated in several types of lymphoma, including splenic marginal zone lymphoma, DLBCL and FL." (PMID 30802265, 2019). "The Notch2 is a critical membrane receptor for B-cell functions, and also displays various biological roles in lymphoma pathogenesis." (PMID 25314575, 2014). "Early studies showed that feline leukemia virus recombinant genomes isolated from lymphomas captured Notch2, which included the intracellular ankyrin repeat functional domain in the envelope gene." (PMID 22128846, 2011). "Panel sequencing of the lymphoma showed mutations in MYD88 (p.Ser219Cys) and NOTCH2 (p.Gln2409Ter)." (PMID 33876323, 2021). "Interestingly, B-cell lymphomas have been reported to produce FGF4, which upregulates Jag1 on adjacent endothelial cells, that in turn induces Notch2 regulation of Hey1 in the lymphoma cells." (PMID 25309874, 2014).
lymphoma (continued). "Increasing evidence suggests that Notch2 may play a role in leukemia and lymphoma." (PMID 22128846, 2011). "Pathogenic variants were obvious in some of the most commonly affected genes in lymphomas, such as BCL2, MYD88, NOTCH2, EZH2, and CD79B, and most of them could be identified in matched LB-originated cfRNA." (PMID 34204385, 2021). "However, these lymphomas show no NOTCH2 or CD21 expression which are characteristic features of the normal MZ B-cell." (PMID 37160922, 2023). "Similarly, in the context of lymphoma, a specific population of lymphoma cells was shown to up-regulate endothelial Jagged1, through the secretion of FGF4, which in turn up-regulates Notch2 and consequently Hey1 in the tumor cells promoting growth, aggressiveness and resistance to chemotherapy." (PMID 26213336, 2015). "Interestingly, our results showed the truncate NOTCH2 could promote lymphoma cell proliferation and had stronger binding ability to RBP-Jκ, compared with the wild-type Notch2." (PMID 25314575, 2014). "Furthermore, there was no expression of NOTCH2/3 on these lymphomas." (PMID 37160922, 2023).
leukemia (18 papers, 2007 to 2025). A malignant (clonal) hematologic disorder, involving hematopoietic stem cells and characterized by the presence of primitive or atypical myeloid or lymphoid cells in the bone marrow and the blood. "For example, NOTCH2 reported as an oncogene promoting leukemia transformation, here cross-linked the NOTCH signaling, miRNAs in cancer, and Th1/Th2 cell differentiation pathways in the relapse sub-network." (PMID 30195757, 2018). "In light of these findings, a better understanding of the Notch receptor family pathogenic role, in particular Notch2, is desirable because it is still incomplete, not only in the physiological development of B lymphocytes but also in leukemia progression and resistance." (PMID 36686759, 2022). "Overexpression of the active form of Notch1 or Notch2 in the human KCL‐22 leukaemia cell line has been reported to inhibit proliferation, accompanied by an increase in Hes1 mRNA levels." (PMID 35122387, 2022). "Mutational analysis was used to map the genetic variants in leukemia, and found that the highest mutations occurred in PDE4DIP, followed by NOTCH2, FANCA, BCR, and ROS1 in almost all leukemia patients." (PMID 32638549, 2020). "In our study, we found NOTCH2, FANCA, BCR, and ROS1 were significantly mutated in 109 Chinese patients with leukemia." (PMID 32638549, 2020). "NOTCH1 and NOTCH2 are involved in neoplastic disease, e.g. leukemia, skin cancers, in human medulloblastomas." (PMID 17593975, 2007). "We next determined the effect of SNDX-5613 on in vivo leukemia-initiating potential of primary PD AML cells harboring MLL-AF9 plus FLT-3 N676T, as well as mutations in KMT2C, KMT2D, NOTCH2, IRF8, ARID1A, VPS13A, and ABCA7, which were determined by whole-exome sequencing." (PMID 35017466, 2022). "Similarly, miR-1246 has also been reported to potentially enhance the cell proliferation of leukemia cells by targeting the Notch2 pathway." (PMID 33893245, 2021). "Previously, NOTCH2, FANCA, BCR, and ROS1 have been described to play an important role in leukemia." (PMID 32638549, 2020). "NOTCH2 as a crucial crosstalk gene connected multiple pathways, including the miRNAs in cancer and the NOTCH-signaling pathway, and it was an important carcinogenic pathway in leukemia." (PMID 30195757, 2018). "In contrast, Notch1 and Notch2 genes were un-methylated in any of the leukemia cell lines and normal controls, while DLL1, DLL3, DLL4 and Hes6 showed only low levels of methylation (9–27%) in these leukemia cell lines." (PMID 23637910, 2013).
diffuse large B-cell lymphoma (17 papers, 2013 to 2025). "In infectious diseases, NOTCH2 is possibly involved in regulating the Epstein–Barr virus latent/lytic status, and 4.3% of hepatitis C virus-positive cells diffuse large B-cell lymphoma have NOTCH2 mutations." (PMID 36338034, 2022). "c.6094C>A mutation of NOTCH2 is considered to be pathogenic (score 0.97) and is described in diffuse large B cell lymphoma and pancreatic ductal adenocarcinoma (PDAC)." (PMID 33503190, 2021). "Active mutations in NOTCH2 are involved in developments of diffuse large B cell lymphoma and marginal zone B-cell lymphoma." (PMID 30285832, 2018). "Specifically, activating NOTCH2 mutations have been identified in marginal zone B-cell lymphoma and diffuse large B-cell lymphoma, and biochemical analyses have detected activation of NOTCH2 as well as NOTCH1 in CLL." (PMID 23825651, 2013). "Moreover, NOTCH2, which is mutated in 20-25% of splenic marginal zone lymphomas, and less than 10% of diffuse large B cell lymphomas, was mutated in 8% of the OAML." (PMID 27566587, 2016). "In this article, we reported that 3 of 69 (4.3%) diffuse large B-cell lymphomas (DLBCLs) exhibited a truncate NOTCH2 mutation at the nucleotide 7605 (G/A) in the cDNA sequence, which led to partial deletion of the C-terminal of PEST (proline-, glutamic acid-, serine- and threonine-rich) domain." (PMID 25314575, 2014). "Notably, the expression of the NOTCH2 Q2140* mutant in tumor cells of diffuse large B-cell lymphoma has been shown to promote resistance to CHOP chemotherapy in animal models." (PMID 41515931, 2025). "Additionally, genomic mutations are also implicated in this process, supported by identified mutations in Neurogenic Locus Notch Homolog Protein (NOTCH) 2, NOTCH1, and Phosphatase and Tensin Homolog (PTEN) in HCV-positive diffuse large B cell lymphoma (DLBCL) patients." (PMID 38654358, 2024). "In typically MYC-driven Burkitt lymphoma, 7% (5/70) carry Notch1 mutations, 8% (5/63) of BCL2-associated diffuse large B-cell lymphoma (DLBCL) carry similar PEST mutations of Notch2, and 6% (2/35) had amplification of the Notch2 locus." (PMID 24959528, 2014). "By contrast, NOTCH2 mutations have been found in other non-Hodgkin B-cell lymphoma subtypes, such as splenic marginal zone lymphoma (SMZL) and diffuse large B-cell lymphoma (DLBCL)." (PMID 29998084, 2018). "Genetic alterations in Notch genes, mainly in Notch1 and Notch2, occur in other B-cell malignancies such as CLL, splenic marginal zone lymphoma, mantle cell lymphoma diffuse large B-cell lymphoma (DLBCL) and, rarely, follicular lymphoma." (PMID 31346528, 2019).
cholestasis (16 papers, 2013 to 2025). Impairment of the bile flow caused by obstruction within the liver, or outside the liver in the bile duct system. "When a NOTCH2 variant is identified during the molecular analysis for cholestasis, only few pathogenic criteria could be considered, due to the scarcity of information about it." (PMID 39202394, 2024). "Our report, together with all other reports about unclassified variants in NOTCH2 gene, could be helpful to enlarge the knowledge of cholestasis-associated variants." (PMID 39202394, 2024). "The elevated NOTCH2 expression is associated with cholestasis-induced liver fibrogenesis." (PMID 35322757, 2022). "The incidence rates of liver-related symptoms, including cholestasis and bile duct paucity, are similar in patients with JAG1- or NOTCH2-associated ALGS." (PMID 40597401, 2025). "This disruption leads to severe cholestasis followed by hepatic necrosis and fibrosis within infancy, as seen in humans with AGS, which is an autosomal dominant disorder evoked by point mutations in JAG1 and less commonly NOTCH2 genes." (PMID 38731931, 2024). "In this study, we reported 11 variants of the NOTCH2 gene, 10 of which were never described before in patients with cholestasis/hepatic diseases." (PMID 39202394, 2024). "Patient #47 underwent a cholestasis panel and was found to have a VUS in NOTCH2, which has been demonstrated to participate in lens development." (PMID 36980880, 2023).
medulloblastoma (16 papers, 2007 to 2021). A malignant, invasive embryonal neoplasm arising from the cerebellum. "In sum, these data corroborate the notion that Notch1 and Notch2 play different roles in medulloblastoma tumor growth." (PMID 29993038, 2018). "Growth rates of DAOYNotch1−/− cells were very similar to that of control DAOY cells, whereas DAOYNotch2−/− cells showed markedly reduced growth, corroborating a specific role for Notch2 in medulloblastoma tumor growth." (PMID 29993038, 2018). "For instance, Notch2 suppresses the effects of Notch1 in mesothelioma, but in medulloblastoma, Notch2 actually stimulates tumorigenesis, whereas Notch1 inhibits it." (PMID 29342862, 2018). "In medulloblastoma, sustained high expression of Notch2 significantly increases the number of medulloblastoma stem cells, whereas the inhibition of Notch signaling decreases the medulloblastoma stem cells and suppresses carcinogenesis." (PMID 29029546, 2017). "For example, in medulloblastomas, NOTCH2 was shown to promote tumorigenesis, whereas NOTCH1 inhibited tumor growth." (PMID 28968975, 2017). "In fact, in medulloblastoma, Notch2 is preferentially expressed in proliferating progenitors, while Notch1 in postmitotic differentiated cells." (PMID 21078177, 2010). "In GBM and in medulloblastoma, the frequency and the intensity of Notch2 expression is higher than that of Notch1." (PMID 21078177, 2010). "Moreover, Notch2 was shown to promote tumorigenesis of medulloblastoma, whereas, Notch1 inhibited tumor growth." (PMID 25601901, 2014). "Furthermore, the elevation of Notch2 and Hes5 in Smoothened-induced medulloblastomas suggests that Hh pathway activation interacts with Notch signaling." (PMID 21379383, 2011). "In medulloblastoma, the most common pediatric brain tumor, the expression of the NOTCH2 receptor is higher than NOTCH1, resulting in the accumulation of the NOTCH2 intracellular domain and its tumor-promoting effect." (PMID 32796631, 2020). "The Eberhart group previously showed that expression of Notch2 but not Notch1 was upregulated in medulloblastoma compared with normal pediatric cerebella, although they did not discriminate between SHH and the other subgroups." (PMID 33762301, 2021). "Medulloblastoma is characterized by an upregulation of the receptor NOTCH2, but not NOTCH1, and an increase in Hes1 expression correlates with poor prognosis." (PMID 32796631, 2020).
liver cancer (15 papers, 2015 to 2025). An epithelial or non-epithelial malignant neoplasm that arises from the liver. "Loss-of-function mutations in components like JAG1 or NOTCH2 are associated with impaired liver regeneration and Alagille syndrome, while heightened Notch activity has been linked to the development of primary liver cancers." (PMID 40980689, 2025). "The higher activation of the NOTCH2 pathway in fusion-positive HBLs is likely to further promote the progression of HBL since NOTCH2 elevation is associated with liver cancer." (PMID 39796711, 2024). "It has been recently shown, for instance, that the nuclear NOTCH2 activity is functionally linked with the self-renewing capacity (stemness) and severity of liver cancer cells making nuclear NOTCH2 an ideal candidate for therapeutic interventions." (PMID 28736522, 2017). "Conversely, suppression of NOTCH2—whose expression correlates with well-differentiated iCCA—significantly decreases tumor growth in various mouse models of liver cancer, including iCCA." (PMID 40980689, 2025). "The transcriptional and immune response regulator (TCIM/C8orf4) inhibits the self-renewal of liver cancer stem cells by suppressing NOTCH2 signaling." (PMID 35614477, 2022). "In contrast, two research groups revealed that the activated intracellular domain of Notch1 or Notch2 induces liver cancer development." (PMID 26416455, 2015). "NOTCH2 also promotes the development of liver cancer in mouse models." (PMID 39796711, 2024). "Interestingly, a recent study demonstrates the suppressive effect of human TC1 on Notch2 signaling in liver cancer stem cells." (PMID 28382040, 2017). "In addition, it has been demonstrated that inhibition of Notch2 regulated by C8orf4 could suppress the self-renewal of liver cancer stem cells(CScs) and Notch2 and Jag1 may function as novel therapeutic targets for HCC treatment." (PMID 29298665, 2018). "It is possible that these findings hold true in the context of liver cancer, as NOTCH2 is amplified in 10% of HCC patients; however, again, further studies are needed to demonstrate a role for tumor-intrinsic Notch signaling in promoting immune escape in the context of liver cancer." (PMID 33981303, 2021).